TNFAIP3 (TNF alpha induced protein 3)
Diseases named in the same sentence as TNFAIP3 in open-access papers (continued):
Sharing a sentence is not in itself a finding about the gene and the disease.
myasthenia gravis (2 papers, 2017 to 2021). Myasthenia gravis (MG) is a rare, clinically heterogeneous, autoimmune disorder of the neuromuscular junction characterized by fatigable weakness of voluntary muscles. "In this study, we intended to genotype 2 single nucleotide polymorphisms (SNPs) of tumor necrosis factor α-induced protein 3 (TNFAIP3) genes and explore an association of TNFAIP3 genetic polymorphism with the patients of myasthenia gravis (MG) at clinical level." (PMID 28514294, 2017).
myocarditis (2 papers, 2021 to 2022). Myocarditis is a condition that is characterized by inflammation of the heart muscle (myocardium). "Up-regulation of Argonaute proteins (AGO1 and AGO3) inhibited the expression of TNFAIP3 in CVB3-induced myocarditis." (PMID 35034631, 2022).
osteoarthritis (2 papers, 2020 to 2022). A noninflammatory degenerative joint disease occurring chiefly in older persons, characterized by degeneration of the articular cartilage, hypertrophy of bone at the margins and changes in the synovial membrane. "Both TRAF1 and TNFAIP3 were previously identified as osteoarthritis-associated markers." (PMID 32674293, 2020). "TNFAIP3 showed differential expression between RA and osteoarthritis synoviocytes." (PMID 35140805, 2022).
periodic fever syndrome (2 papers, 2018 to 2025). Fevers of unknown etiology recurring over months or years.
PFAPA syndrome (2 papers, 2025). An auto inflammatory syndrome characterized by recurrent febrile episodes associated with aphthous stomatitis, pharyngitis and cervical adenitis. "We have found a novel mutation in the gene TNFAIP3 in an adult patient with periodic fever, aphthous stomatitis, pharyngitis, and adenitis—the PFAPA syndrome, under the environmental factor‐COVID‐19 vaccination." (PMID 40071725, 2025). "Followed by detailed clinical inquiry, related laboratory tests, genetic sequencing and treatment, we reported a case with the adult‐onset of PFAPA syndrome with a novel TNFAIP3 mutation." (PMID 40071725, 2025).
pulmonary fibrosis (2 papers, 2023 to 2024). Chronic progressive interstitial lung disorder characterized by the replacement of the lung tissue by connective tissue, leading to progressive dyspnea, respiratory failure, or right heart failure. "The shared gene TNFAIP3 is associated with airway inflammatory responses although it is a negative regulator of inflammation These results indicated the potential function of shared genes which regulated by common miRNAs in the SLE-derived pulmonary fibrosis." (PMID 36871016, 2023).
retinal degeneration (2 papers, 2010 to 2014). Degeneration of the retina. "The Tnfaip3 message of this anti-apoptotic gene was reported to be downregulated in different models of retinal degeneration." (PMID 20577653, 2010). "The hypothesis is that a higher activity of Tnfaip3 in B6a confers protection against retinal degeneration." (PMID 20577653, 2010).
rheumatic disease (2 papers, 2013 to 2014). "Previously, plenty of GWAS and candidate gene association studies suggested TNFAIP3 gene loci rs2230926 and rs5029939 were associated with diverse rheumatic diseases." (PMID 25337792, 2014).
sarcoma (2 papers, 2018 to 2021). A usually aggressive malignant neoplasm of the soft tissue or bone. "In addition to shared clonal abnormalities, additional aberrancies were detected in the sarcoma tumor cells, including deletion of a subclone of BRAF (G466A), loss of TRAF3 R505 and new clonal mutations in NF1 and TNFAIP3." (PMID 29463311, 2018).
scleritis (2 papers, 2020 to 2022). Inflammation of the sclera. "In our study, weak associations were detected between two SNPs in the TNFAIP3 gene and scleritis." (PMID 33287909, 2020). "In this study, haplotype analysis showed that a TNFAIP3 TGT haplotype, a TNFSF4 GT haplotype, and a TNFSF15 CCC haplotype were significantly associated with scleritis." (PMID 33287909, 2020). "In conclusion, we identified the association of various TNF gene related haplotypes with scleritis in Chinese Han, including TGT in TNFAIP3, GT in TNFSF4, and CCC in TNFSF15." (PMID 33287909, 2020). "We observed that one TNFAIP3 haplotype TGT was protective for developing scleritis, and this specific association has to our knowledge not been found in other diseases." (PMID 33287909, 2020). "Two SNPs, rs9494885 and rs2230926 in TNFAIP3, were correlated with scleritis." (PMID 33287909, 2020). "This study reveals that a TGT haplotype in TNFAIP3 may be a protective factor for the development of scleritis and that a GT haplotype in TNFSF4 and a CCC haplotype in TNFSF15 may be risk factors for scleritis in Chinese Han." (PMID 33287909, 2020). "Additional studies are necessary to investigate whether TNFAIP3 haplotypes might also have an impact on the therapeutic response of scleritis patients to biological agents." (PMID 33287909, 2020). "In addition, a study on the genotypes of TNF-α-related genes in Chinese Han patients with scleritis found that specific haplotypes in TNFAIP3 (TNF-α-induced protein 3), TNFSF4 (TNF-αreceptor superfamily member 4), and TNFSF15 might be the risk or protective factors of scleritis in Chinese Han." (PMID 36431163, 2022).
stomatitis (2 papers, 2021 to 2024). Inflammation of the oral mucosa due to local or systemic factors. "Recurrent stomatitis is the most common symptom in HA20 patients caused by single nucleotide variations, small insertions, or small deletions in TNFAIP3." (PMID 38183052, 2024). "Although the TNFAIP3 gene was not described in that report, HA20 patients also present with early-onset BD-like symptoms, PFAPA, and recurrent stomatitis, so HA20 might be associated with BSDs." (PMID 33549127, 2021).
T-cell large granular lymphocytic leukemia (2 papers, 2021). "Furthermore, TNFAIP3 mutations significantly correlated with T-cell large granular lymphocytic leukemia (T-LGLL) with a favorable prognosis in the JNU dataset (P = 0.002)." (PMID 34526012, 2021).
vitiligo (2 papers, 2022 to 2024). Generalized well circumscribed patches of leukoderma that are generally distributed over symmetric body locations and is due to autoimmune destruction of melanocytes. "Interestingly, through MR analysis, we identified TNFRSF11B, TNF alpha induced protein 3 (TNFAIP3), TNF superfamily member 12 (TNFSF12) as potentially protective factors against vitiligo, which may explain why some patients experience depigmentation after using TNF inhibitors." (PMID 38660673, 2024).
ZIKV infection (2 papers, 2023 to 2025). "In HeLa cells, ZIKV infection downregulates A20 protein expression despite elevated TNFAIP3 mRNA levels." (PMID 41472303, 2025).
acute kidney injury (1 paper, 2024). Sudden and sustained deterioration of the kidney function characterized by decreased glomerular filtration rate, increased serum creatinine or oliguria. "In a mouse model of acute kidney injury, rare variants in the TNFAIP3 (TNF alpha-induced protein 3) gene were identified as having anti-inflammatory effects, and as such they were deemed ‘protective’48." (PMID 39127776, 2024).
acute myeloid leukemia (1 paper, 2025). Acute myeloid leukemia (AML) is a group of neoplasms arising from precursor cells committed to the myeloid cell-line differentiation. "Furthermore, TNFAIP3 enhanced the resistance of GBM and acute myeloid leukemia (AML) cells to O6 alkylating agents and daunorubicin, respectively." (PMID 40469292, 2025).
acute pancreatitis (1 paper, 2014). An acute inflammatory process that leads to necrosis of the pancreatic parenchyma. "We enrolled 201 healthy controls and 190 acute pancreatitis patients (including 47 systemic inflammatory response syndrome patients) for this study and used DNA sequencing to investigate polymorphisms in the TNFAIP3 promoter." (PMID 25050625, 2014). "However, only a few studies have focused on the relationship between TNFAIP3 polymorphisms and acute pancreatitis (AP)." (PMID 25050625, 2014).
adenomyosis (1 paper, 2025). The growth of endometrial tissue inside the muscular wall of the uterine corpus. "Our transcriptomic analysis identified TNFAIP6, matrix metalloproteinase 7 (MMP7), TNFAIP3, leukemia inhibitory factor (LIF), and serum and glucocorticoid-regulated kinase 1 (SGK1) as the top 5 genes implicated in the inflammatory mechanisms of adenomyosis." (PMID 40989079, 2025). "Dysregulation of TNFAIP3 may lead to the prolonged inflammatory state seen in adenomyosis." (PMID 40989079, 2025).
airway hyperresponsiveness (1 paper, 2019). "TNFAIP3 is an inhibitor of NF-κB that was reported to reduce airway leukocyte recruitment, peribronchoalveolar inflammation and mucus production and airway hyperresponsiveness (AHR) in mice subjected to OVA sensitization/challenge." (PMID 31805682, 2019).
anaplastic large cell lymphoma (1 paper, 2021). Anaplastic large cell lymphoma (ALCL) is a rare and aggressive peripheral T-cell non-Hodgkin lymphoma, belonging to the group of CD30-positive lymphoproliferative disorders, which affects lymph nodes and extranodal sites. "The CTCL mutation frequency was relatively high, reaching 6.3%, and no TNFAIP3 mutations were found in anaplastic large cell lymphoma (ALCL), NKTCL, hepatosplenic T-cell lymphoma (HSTCL), or large granular T lymphocyte leukemia (T-LGLL)." (PMID 34526012, 2021).
angiosarcoma (1 paper, 2021). A malignant tumor arising from the endothelial cells of the blood vessels. "For example, DLC1 (a RhoGAP) deregulates the expression of TNFAIP3/A20 and upregulates the expression of BCL211/BIM and caspase-3 to induce cell death by inactivating NF-кB signaling in angiosarcoma." (PMID 34663417, 2021).
ankylosis (1 paper, 2017). Fixation and immobility of a joint. "We did note a correlation between TNFAIP3 and duration of disease, so those with longer standing disease and ankylosis may be in a more “burned out,” less inflammatory stage of disease." (PMID 28791018, 2017).
arteriosclerosis (1 paper, 2021). A vascular disorder characterized by thickening and hardening of the walls of the arteries. "Impaired TNFAIP3 expression increases inflammation and transplant arteriosclerosis in mice." (PMID 34831306, 2021).
autism spectrum disorder (1 paper, 2021). A spectrum of developmental disorders that includes autism, and Asperger syndrome. "We have since discovered compound heterozygous TNFAIP3 mutations explaining the child’s autoimmunity, but it was notable that E54K had been independently found as a heterozygous de novo mutation in a child with autism spectrum disorder." (PMID 33914737, 2021).
bacterial meningitis (1 paper, 2015). Inflammation of the membranes surrounding the brain and spinal cord due to a bacterial infection. "Most interestingly, these factors may positively (e.g., IL33 and IL18rap) and negatively (Tnfaip3, CISH and Zfp36) contribute to regulation of NF-κB, which is a hallmark feature of bacterial meningitis." (PMID 25993608, 2015).
bacterial pneumonia (1 paper, 2022). Acute infection of the lung parenchyma caused by bacteria (e.g., Streptococcus pneumoniae, Haemophilus influenzae, Chlamydia pneumoniae, Mycoplasma pneumoniae, and Legionella pneumophila). "They identified the PGC-1α/TNFAIP3 axis as a mechanism responsible for the homeostatic role of the telomere, and the disturbance in this axis led to inflammatory Terc−/− macrophages and severe bacterial pneumonia in Terc−/− mice." (PMID 35013155, 2022).
bipolar I disorder (1 paper, 2021). A bipolar disorder that is characterized by at least one manic or mixed episode. "In the PBMC of adolescents diagnosed bipolar I disorder, TNFAIP3 mRNA level correlated with pediatric inpatient aggression prediction score, as well as functional brain activations of right anterior part of anterior cingulate gyrus, a part of aggression pathway." (PMID 34393859, 2021).
blood disease (1 paper, 2021). A disease that occurs in the blood. "The top candidates include TNFAIP3, which has been reported before, but also include other, novel regions, containing genes involved in blood diseases (CYCS), neurological diseases (PRKCH, KCNH5, LRNN1), metabolism (SFRP4, SUMF1), and skin development (ASCL4, RAB27A)." (PMID 34032215, 2021).
breast ductal carcinoma (1 paper, 2023). "At the protein level, via immunohistochemistry, a weak expression of CD274 and moderate expression of ferroptosis drivers (IFNG, TNFAIP3 and IDO1) were observed in biopsy of ductal breast carcinoma." (PMID 38201582, 2023). "The tumoral expression of CD274, TNFAIP3, IFNG and IDO1 in biopsy of breast ductal carcinoma was confirmed at the protein level via immunohistochemistry imaging." (PMID 38201582, 2023).
Burkitt lymphoma (1 paper, 2014). A rare form of malignant mature B-cell non-Hodgkin lymphoma. "More so, TNFAIP3 gene was expressed at lower levels in GCB DLBCL cell lines than in Burkitt’s lymphoma cell lines." (PMID 25364581, 2014).
cerebral infarction (1 paper, 2021). An ischemic condition of the brain, producing a persistent focal neurological deficit in the area of distribution of the cerebral arteries. "Two weeks after injection of LV-TNFAIP3, the neurological function score and cerebral infarction area were lowered indicative of the therapeutic effect of TNFAIP3 in mice." (PMID 34853620, 2021).
cholesteatoma (1 paper, 2012). A pathologic process characterized by the proliferation of keratinizing squamous epithelium resulting in the accumulation of keratin and cells in the middle ear and/or mastoid. "Genes for anti-apoptotic proteins such as Bcl-xl (BCL2L1), A20 (TNFAIP3) and cIAP2 (BIRC3) show only a slightly higher expression in cholesteatoma (logFC 1.5–3)." (PMID 23285167, 2012).
chronic obstructive pulmonary disease (1 paper, 2025). A chronic and progressive lung disorder characterized by the loss of elasticity of the bronchial tree and the air sacs, destruction of the air sacs wall, thickening of the bronchial wall, and mucous accumulation in the bronchial tree. "This study identifies TNFAIP3 as a key molecular target linking chronic obstructive pulmonary disease (COPD) and insomnia, and proposes berbamine as a potential therapeutic drug, filling the gap in understanding shared mechanisms and dual-treatment strategies for this comorbidity." (PMID 41155519, 2025). "In the treatment of chronic obstructive pulmonary disease (COPD) complicated by insomnia, the mechanisms of action of TNFAIP3 and Berbamine have attracted considerable attention." (PMID 41155519, 2025). "In exploring the mechanism of action of Berbamine on TNFAIP3 and its potential application in treating the co-morbidity of chronic obstructive pulmonary disease (COPD) and insomnia, we require a thorough understanding of TNFAIP3’s role in cellular survival and inflammatory regulation." (PMID 41155519, 2025).
Cornelia de Lange syndrome (1 paper, 2025). A rare syndrome characterized by low birth weight, delayed growth, intellectual disabillity, behavioral problems, and a distinctive facial appearance (thin, arched eyebrows, low set ears, small teeth, and small nose). "Our study provides the first molecular description of the co-occurrence of Cornelia de Lange syndrome (CdLS) and generalized pustular psoriasis (GPP), highlighting the potential mechanistic convergence of RAD21 and TNFAIP3 mutations." (PMID 41226818, 2025).
cutaneous T cell lymphoma (1 paper, 2020).
disc degeneration (1 paper, 2020). "In conclusion, our findings initially reveal the relationship between TNFAIP3, autophagy, inflammation and disc degeneration, and further illuminate the mechanism by which TNFAIP3 regulates autophagy of human NPCs in inflammatory stimulation." (PMID 33226960, 2020).
E. coli infection (1 paper, 2019). "In our work, we observed the upregulation of TNFAIP3 in hBMECs, mediated by meningitic E. coli infection-caused decrease of miR-19b-3p." (PMID 31783671, 2019). "Taken together, these data robustly support our narrative that TNFAIP3 is directly and negatively regulated by miR-19b-3p in hBMECs in response to meningitic E. coli infection." (PMID 31783671, 2019). "As expected, both real-time PCR and Western blotting showed that TNFAIP3 expression exhibited a significant increase in hBMECs along with meningitic E. coli infection, which exhibited the exact opposite trend as that of the miR-19b-3p." (PMID 31783671, 2019). "We demonstrated in vivo and in vitro that meningitic E. coli infection of BMECs could downregulate miR-19b-3p that led to attenuated production of proinflammatory cytokines and chemokines via the TNFAIP3/NF-κB axis." (PMID 31783671, 2019). "Since miR-19b-3p was shown to be involved in meningitic E. coli infection, whether it also functioned through TNFAIP3 was unclear and needed to be further revealed." (PMID 31783671, 2019). "Here, we demonstrated in vivo and in vitro that meningitic E. coli infection of BMECs significantly downregulated miR-19b-3p, which led to attenuated production of proinflammatory cytokines and chemokines via increasing the expression of TNFAIP3, a negative regulator of NF-κB signaling." (PMID 31783671, 2019).
eczema (1 paper, 2021). "Skin involvement was remarkable in TNFAIP3 and ADA2 deficiencies, but it was one of the most common manifestations among ALPS-like disorders, mainly in form of non-infectious skin rashes, psoriatic-like lesions, skin abscess, severe eczema and skin warts (usually due to papilloma virus infection)." (PMID 34447369, 2021).
endotoxemia (1 paper, 2023). "Exogenous CO or heme-induced HO-1 can inhibit LPS-induced TNF-α production through the upregulation of the immune response gene 1 (IRG1)/tumor necrosis factor and alpha-inducible protein 3 (TNFAIP3 or A20) pathway to suppress endotoxemia inflammation in mice." (PMID 36810201, 2023).
erythroderma (1 paper, 2025). "In this case, the clinical features of patient with CdLS phenotype correlated with RAD21 gene alterations, while TNFAIP3 modifications were consistent with her history of erythematous, scaly, and pruritic plaques, culminating in erythroderma." (PMID 41226818, 2025).
esophageal squamous cell carcinoma (1 paper, 2021). Esophageal squamous cell carcinoma (ESCC) is a type of esophageal carcinoma (EC) that can affect any part of the esophagus, but is usually located in the upper or middle third. "However, increased TNFAIP3 expression was linked to low survival rate of esophageal squamous cell carcinoma in a non-cancerous esophageal cell line." (PMID 34500744, 2021).
esophagitis (1 paper, 2025). An acute or chronic inflammatory disease affecting the esophageal wall. "In the current research, the likely pathogenic variant in the TNFAIP3 gene was associated with cutaneous, vascular, and joint manifestation, as well as ILD and esophagitis." (PMID 41283471, 2025). "The chr6:138199775 T/TC substitution in the TNFAIP3 gene, classified as likely pathogenic, was identified in two SSc patients and associated with cutaneous, vascular, and joint manifestation, as well as ILD and esophagitis (χ2 = 16.3–40.9, p < 0.0001)." (PMID 41283471, 2025).
gastric MALT lymphomas (1 paper, 2021). "The frequency of TNFAIP3, TET2, and NOTCH1 mutations in H. pylori negative gastric MALT lymphoma is similar to those seen in unselected gastric MALT lymphomas, whereas the previously reported TNFRSF14 alterations affecting gastric MALT lymphomas were absent in the current series." (PMID 34203889, 2021).